VAV2 (vav guanine nucleotide exchange factor 2)
Description:
Guanine nucleotide exchange factor for the Rho family of Ras-related GTPases. Plays an important role in angiogenesis. Its recruitment by phosphorylated EPHA2 is critical for EFNA1-induced RAC1 GTPase activation and vascular endothelial cell migration and assembly (By similarity).
Synonyms: VAV-2
Tractability: Antibody: its Gene Ontology location is reachable by antibodies, with medium confidence. PROTAC: ubiquitination databases record sites on it; its protein half-life has been measured.
Gene: Protein-coding gene on chromosome 9 (133,761,892 to 133,992,854, reverse strand). Ensembl gene ENSG00000160293.
Subcellular location (Human Protein Atlas): Vesicles
Pathways (Reactome):
Signal Transduction: CDC42 GTPase cycle; G alpha (12/13) signalling events; NRAGE signals death through JNK; RAC1 GTPase cycle; RAC2 GTPase cycle; RAC3 GTPase cycle; RHOA GTPase cycle; RHOB GTPase cycle; RHOC GTPase cycle; RHOG GTPase cycle; VEGFA-VEGFR2 Pathway; VEGFR2 mediated vascular permeability
Immune System: DAP12 signaling; FCERI mediated Ca+2 mobilization; FCERI mediated MAPK activation; Regulation of actin dynamics for phagocytic cup formation
Developmental Biology: EPH-ephrin mediated repulsion of cells; Signal transduction by L1
Cell-Cell communication: SRC activates STAT3 in a quantitative manner, through Cadherin-11 (CDH11), RAC1 and gp130 (IL6ST)
Disease: FCGR3A-mediated phagocytosis
Drug ADME: Azathioprine ADME
Hemostasis: GPVI-mediated activation cascade
Gene Ontology:
Molecular function: guanyl-nucleotide exchange factor activity; phosphotyrosine residue binding; protein binding; epidermal growth factor receptor binding
Biological process: cell migration; cellular response to xenobiotic stimulus; Fc-epsilon receptor signaling pathway; Fc-gamma receptor signaling pathway involved in phagocytosis; immune response-regulating cell surface receptor signaling pathway; platelet activation; positive regulation of phosphatidylinositol 3-kinase/protein kinase B signal transduction; regulation of small GTPase mediated signal transduction; signal transduction; small GTPase-mediated signal transduction; vascular endothelial growth factor receptor signaling pathway; intracellular signal transduction; response to xenobiotic stimulus
Cellular component: cytoplasm; cytosol; plasma membrane
Genetic constraint (gnomAD): Loss-of-function variants: 65 observed, 128.27 expected, observed/expected ratio (o/e) 0.51, 90% interval 0.41 to 0.62. The upper end of that interval is the gene's LOEUF score, 0.62, which puts it in group 2 of 6, group 1 being the genes least tolerant of losing a copy. Missense variants: 923 observed, 1,153.2 expected, observed/expected ratio (o/e) 0.8, 90% interval 0.76 to 0.85. Synonymous variants: 481 observed, 440.98 expected, observed/expected ratio (o/e) 1.09, 90% interval 1.01 to 1.18.
Homologues: Orthologues: chimpanzee VAV2 (99% identical), macaque VAV2 (99% identical), dog VAV2 (96% identical), rat Vav2 (95% identical), mouse Vav2 (95% identical), pig VAV2 (95% identical), guinea pig VAV2 (84% identical), tropical clawed frog vav2 (83% identical), zebrafish vav2 (82% identical). Paralogues in human: VAV3 (53% identical), VAV1 (50% identical), MCF2L (16% identical), PLEKHG4B (16% identical), TRIO (16% identical), KALRN (15% identical), ARHGEF7 (15% identical), PLEKHG4 (14% identical), TIAM1 (14% identical), TIAM2 (14% identical), ARHGEF40 (13% identical), PLEKHG1 (13% identical), and 10 more.
Diseases named in the same sentence as VAV2 in open-access papers:
VAV2 is named in the same sentence as 77 diseases in open-access papers, as found by Europe PMC text mining. Sharing a sentence is not in itself a finding about the gene and the disease. The quoted sentences say what the papers report.
breast cancer (24 papers, 2010 to 2025). A primary or metastatic malignant neoplasm involving the breast. "This is probably due to the functional link of this Vav2;Vav3-dependent signature with the tumorigenic and lung-associated metastasis properties of breast cancer cells." (PMID 30087437, 2019). "By contrast, there are specific functions associated with the maintenance of breast cancer epithelial integrity that can be redundantly performed by Vav2 and Vav3." (PMID 31100928, 2019). "(ii) A mirror-image expression of the NR2F1 transcript with those encoding the Vav2, Vav3 and E-cadherin proteins in a large variety of human breast cancer cell lines." (PMID 30087437, 2019). "We have reported here that Vav2 and Vav3 contribute to maintain the epithelial phenotype and associated molecular traits of breast cancer cells." (PMID 30087437, 2019). "However, Vav2 is a critical regulator of growth factor-stimulated motility in human cancers and Vav2 signaling has been implicated in cancer cell invasion and angiogenesis of human breast cancer cells and ovarian cancer cells." (PMID 23724134, 2013). "Mechanistically, the overexpression of MST3 increases the phosphorylation of VAV2, and subsequently promotes VAV2-mediated activation of the Rac1-cyclin D1 signaling pathway that is required for the growth of breast cancer cells." (PMID 37202821, 2023). "VAV2 is highly expressed in a variety of tumor cells and tissues, including lung cancer, thyroid papillary carcinoma, and breast cancer." (PMID 35528244, 2022). "One study showed that diosgenin suppressed the phosphorylation of Vav2 and activation of Cdc42, leading to attenuation of cell migration of breast cancer cells, indicating that diosgenin has a therapeutic potential for metastasis therapy." (PMID 32626765, 2020). "In breast cancer, Vav2 activates Rac1/3 to regulate actin polymerization, invadopodia extension, matrix degradation, vesicular trafficking, and invasion." (PMID 32322580, 2020). "In breast cancer specimens, Vav2 expression was significantly higher in invasive cancer tissues compared to ductal carcinoma in situ or normal breast tissue." (PMID 32322580, 2020). "Conversely, the ectopic expression of an active version of Vav2 promotes mesenchymal-epithelial transitions using E-cadherin-dependent and independent mechanisms depending on the mesenchymal breast cancer cell line used." (PMID 30087437, 2019). "In the case of breast cancer, we have recently shown that the expression of Vav2 and Vav3 is important for both the primary tumorigenesis and lung metastasis formation." (PMID 30087437, 2019). "During an earlier work aimed at characterizing the role of Vav2 and Vav3 in breast cancer, we generated a collection of Vav2 (KD2), Vav3 (KD3), and double Vav2;Vav3 (KD2/3) knockdown 4T1 cells." (PMID 30087437, 2019). "We have previously identified a number of Vav2;Vav3-dependent distal transcriptional targets in breast cancer cells." (PMID 30087437, 2019). "The in silico analysis of microarray datasets also suggested that the abundance of VAV2 and VAV3 transcripts is associated with low and high levels of CDH1 and NR2F1 transcripts in human breast cancer cell lines, respectively." (PMID 30087437, 2019). "For example, the analysis of the Vav-dependent transcriptome of breast cancer cells using genome expression profiling experiments has revealed that some of the Vav2-dependent genes can be also regulated when using a catalytically-dead Vav2 protein." (PMID 31100928, 2019). "Genome expression profiling experiments further indicate that Vav2 and Vav3 promote both common and family member-specific changes in the transcriptome of breast cancer cells." (PMID 31100928, 2019). "Alternatively, the Rac1 GEFs P-Rex1, Vav2/3, and Dock1 have been shown to contribute to metastatic behavior in particular breast cancer subtypes." (PMID 29769144, 2018).
breast cancer (continued). "Our results suggest that MST3/VAV2/cyclin D1 is one of the important oncogenic pathways in breast cancer development, but breast cancer development requires a coordination of MST3 pathway and other oncogenic pathways." (PMID 26910843, 2016). "MST3 induces cyclin D1 by binding VAV2 and enhancing Rac1 activation to promote the tumorigenicity of breast cancer." (PMID 26910843, 2016). "Vav2 acts downstream of the Eph A and B receptors in the receptor pathway and its perturbation in breast cancer progression is very relevant to the work we undertook in HT29 cells." (PMID 20624275, 2010). "It has recently come to light that in breast cancer tissue the levels of Vav2 expression as compared to normal or hyperplasic epithelium are down-regulated." (PMID 20624275, 2010). "The importance of the downregulation of miR-200c is further underscored using GSEAs, as they reveal that a large percentage of the previously characterized miR-200c-regulated transcriptome of endometrial and breast cancer cells becomes upregulated upon depletion of Vav2 and Vav3 in 4T1 cells." (PMID 30087437, 2019). "Here, we report that the Rho GTPase activators Vav2 and Vav3 utilize a new Rac1-dependent and miR-200c-dependent mechanism that maintains the epithelial state by limiting the abundance of the Zeb2 transcriptional repressor in breast cancer cells." (PMID 30087437, 2019). "In breast tumors, contrarily to Vav2 and Vav3, that play synergistic roles in breast cancer by sustaining tumor growth, neo-angiogenesis and metastasis, the Vav1 transcript seems to be higher in tumors from patients that remained disease free than in patients who developed recurrence." (PMID 24962430, 2014). "In addition, we monitored the expression pattern in those samples of Vav2/Vav3-dependent genes that were common between breast cancer cells and TPA-stimulated keratinocytes." (PMID 23935450, 2013). "Therefore, Vav2 is a central regulator of breast cancer metastasis." (PMID 32322580, 2020). "Likewise, GSEAs reveal high levels of inverse correlation between the Vav2;Vav3-dependent 4T1 transcriptome and the mRNA landscape induced by the ectopic expression of the entire miR-200 cluster in mesenchymal 4TO7 breast cancer cells (which express very low amounts of both miR-200c and E-cadherin)." (PMID 30087437, 2019). "Furthermore, VAV2 is essential for the oncogenic activity of MST3 in breast cancer." (PMID 26910843, 2016). "The PRL-mediated activation of Nek3 contributes differentially to VAV2 signaling pathways involving Rac1 and signal transducer and activator of transcription 5 and implicates Nek3 during PRL-mediated actions in breast cancer." (PMID 40160874, 2025). "This study highlights the critical role of two VAV family members, VAV2 and VAV3, in regulating the mevalonate pathway in breast cancer cells through a RAC1‐ and SREBF‐dependent mechanism." (PMID 39119789, 2025). "This led us to identify several VAV2;VAV3‐regulated distal elements that are involved in specific stages of the metastatic program of breast cancer cells to the lung." (PMID 39119789, 2025). "Our proteomic analysis revealed proteomic profile alteration in MDA-MB-231 upon CB exposure that potentially led to breast cancer suppression, such as ZPR1/SHC1/MAPK-mediated cell proliferation and AXL/VAV2/RAC1-mediated cell motility pathways." (PMID 39527598, 2024). "In triple negative breast cancer cell lines, Vav2 was shown to interact with NEDD9, a scaffolding protein involved in cell migration and thus, activate Rac1 in breast cancer cell lines." (PMID 32322580, 2020). "For example, the Rac1 GEFs P-Rex1 and Vav2/3 contribute to metastasis in luminal subtype breast cancers, while the Rac1 GEF Dock1 controls metastasis in HER2-positive breast cancers." (PMID 29769144, 2018).
breast cancer (continued). "In the present study, we report that the expression of mevalonate pathway enzymes is mediated by the RHO guanosine nucleotide exchange factors VAV2 and VAV3 in a RAC1‐ and sterol regulatory element‐binding factor (SREBF)‐dependent manner in breast cancer cells." (PMID 39119789, 2025). "Finally, GEFs like VAV2 showed to be important in squamous carcinomas of the head and neck and VAV3 in glioblastoma and breast cancer." (PMID 32351958, 2020). "Interestingly, we have also observed that constitutively active Vav2 can promote epithelial features in the mesenchymal 67NR and 4TO7 breast cancer cells in the absence of reexpression of the Cdh1 mRNA and other epithelial phenotype-associated transcripts." (PMID 30087437, 2019). "In addition, we describe novel results for Vav2 protein, whose protein expression in early stage breast cancer had not been investigated." (PMID 25785189, 2014).
head and neck squamous cell carcinoma (8 papers, 2014 to 2025). A squamous cell carcinoma that arises from any of the following anatomic sites: lip and oral cavity, nasal cavity, paranasal sinuses, pharynx, larynx, and salivary glands. "In head and neck squamous cell carcinoma, VAV2 activity forms a Rho-Myc-YAP signaling axis responsible for promoting a stem cell-like regenerative proliferation of tumor cells." (PMID 37986175, 2023). "Here, the authors find that the Rho GEF VAV2 is over expressed in both cutaneous and head and neck squamous cell carcinomas and that at the molecular level VAV2 promotes a pro-tumorigenic stem cell-like signalling programme." (PMID 32963234, 2020). "Previous studies have shown that VAV2 overexpression has resulted in increased invasion in oral squamous cell carcinoma and head and neck squamous cell carcinoma." (PMID 25277193, 2014). "VAV guanine nucleotide exchange factor 2 (VAV2) is hyperactivated in head and neck squamous cell carcinoma, and its molecular role was assessed by VAV2-silencing; this investigation revealed that inactivated Rac1 signaling leads to a decreased invasiveness of cancers." (PMID 27145964, 2016). "In line with this, VAV2 was recently shown as frequently overexpressed in both cutaneous squamous cell carcinoma (cSCC) and head and neck squamous cell carcinoma (hnSCC) tumors." (PMID 34571765, 2021). "In addition, pharmacological inhibition of CCL2/CCR4/Vav2/Rac1/MLC signaling pathway can effectively reduce the motility of cancer cells, thereby inhibiting local invasion and distant lymph node metastasis in head and neck squamous cell carcinoma (HNSCC) cells." (PMID 41341593, 2025).
lung carcinoma (8 papers, 2015 to 2025). "For example, the c-Src SH2 domain exhibits loss of affinity for Vav2 at the Y142 phosphorylation site in the presence of a lung cancer variant, R143L." (PMID 39764007, 2025). "Guanine nucleotide exchange factor (VAV2) was associated with lung cancer cell adhesion by regulating focal adhesion kinase activity." (PMID 38259849, 2023). "In addition, the IF protein vimentin, VAV2, and Rac1 interact in the regulation of the invasive capacity of lung cancer cells by controlling the formation of focal adhesions via FAK." (PMID 29152145, 2017). "In lung cancer cells, phosphorylated Rac1 GEF VAV2 colocalizes with FAK at focal adhesion sites and activates Rac1 signaling, allows FAK phosphorylation, and promotes cell attachment in vimentin-expressing cells." (PMID 25965826, 2015). "Interestingly, using a phosphoproteomic screen in lung cancer cells, the Rac1 guanine nucleotide exchange factor (GEF) VAV2 was identified as a downstream target of vimentin which induces VAV2 phosphorylation and the localization to FAs where it activates Rac1." (PMID 35990612, 2022).
Hypertension (7 papers, 2008 to 2023). The presence of chronic increased pressure in the systemic arterial system. "Consistent with this idea, the development of the hypertension and its associated cardiovascular comorbidities can be prevented in Vav2–/– and vSMC-specific Rac1–/– mice using sildenafil treatments." (PMID 34571735, 2021). "Due to this, the inactivation of the Vav2 gene leads to defective B cell responses, hypertension, and hypertension-associated comorbidities in mice." (PMID 31100928, 2019). "Vav2 knockout mice have shown defects in heart, arterial walls, and kidneys, as well as tachycardia and hypertension, each associated with adrenaline regulation." (PMID 18613952, 2008). "However, it is worth noting that genetic association studies have found associations of specific VAV2 and VAV3 gene polymorphisms with the development of functions found in mice such as cardiovascular homeostasis, hypertension, obesity, and diabetes." (PMID 34571735, 2021). "For example, Vav2L332A/L332A mice do not develop the hypertension and glaucoma problems that are detected in Vav2−/− mice, indicating that the cells associated with those pathologies can function well with 30% of the normal levels of Vav2 catalytic activity." (PMID 33199701, 2020). "The combined used of Vav2–/– and Vav3–/– mice also demonstrated that hypertension does not contribute per se to the development of type II diabetes and metabolic syndrome." (PMID 34571735, 2021).
glioma (6 papers, 2013 to 2024). A benign or malignant brain and spinal cord tumor that arises from glial cells (astrocytes, oligodendrocytes, ependymal cells). "For example, tRFdb-3003a/b was found to restrain VAV2 expression via binding to the 3’UTR regions of VAV2 in gliomas." (PMID 38289488, 2024). "In agreement with the published literature, we find that suppression of SFK activity with dasatinib in SF767 glioma cells inhibits p120 Y228 phosphorylation, Vav2 Y172 phosphorylation, and Rac1 activation, and blocks their directed migration in culture." (PMID 23457577, 2013). "The tRNA-Cys-GCA derived tRFdb-3003a and tRFdb-3003b might act as key player in tumor progressions of gliomas; tRFdb-3003a/b might directly bind to VAV2 and regulate VAV2 expressions in gliomas." (PMID 36426134, 2022). "Furthermore, in vitro experiments showed that expression levels of VAV2 protein and mRNA were decreased in glioma cells transfected with tRFdb3003a/b-mimic." (PMID 36426134, 2022). "Overexpression of tRFdb-3003a/b could down-regulated the expression levels of VAV2 protein and mRNA in glioma cells." (PMID 36426134, 2022). "Bioinformatics analysis showed the interaction relationships of tRFdb-3003a/b and their predicted target-mRNAs, and found tRFdb-3003a/b may target to the 3′-UTR regions of VAV2, which was overexpressed in gliomas." (PMID 36426134, 2022). "Moreover, tRFdb-3003a/b could directly bind to the 3′-UTR regions of VAV2 and regulate VAV2 expression in gliomas." (PMID 36426134, 2022). "Moreover, overexpression of tRFdb-3003a/b could decrease the expressions of VAV2 protein and mRNA within glioma cells." (PMID 36426134, 2022). "In addition, the analyses of GSE4290 dataset and clinical specimens demonstrated that VAV2 was upregulated in gliomas compared to non-tumors tRFdb-3003a and tRFdb-3003b were down-regulated in gliomas." (PMID 36426134, 2022).
melanoma (6 papers, 2009 to 2025). A malignant, usually aggressive tumor composed of atypical, neoplastic melanocytes. "APOH was negatively correlated with regulatory T cells in primary melanomas, whereas VAV2 was positively correlated with CD8 T cells, but negatively with dendritic cells." (PMID 40943183, 2025). "Interestingly, this TGF-β activity also correlated with expression of an experimentally validated 6-gene “metagene” (VAV2, CORO1A, EPB41L1, CCT4, FRAP1, GJB3) reflecting integrin β1 activity, further supporting a link between integrin activity and TGF-β activity in human melanoma." (PMID 28448494, 2017). "Other cell lines with a negative correlation between VAV2 and STAT1 included the leukemias CCRFCEM and SR, the melanoma M14, the non-small cell lung cancers H226 and H460, and the prostatic adenocarcinoma PC3." (PMID 30653502, 2019).
gastric cancer (5 papers, 2021 to 2025). A primary or metastatic malignant neoplasm involving the stomach. "K/D of NINJ2 led to a significant decrease in VAV2 phosphorylation in ECF-R gastric cancer cells, which further reduced cell viability after ECF treatment." (PMID 40518514, 2025). "Moreover, they discovered that AFAP1L1 induction facilitated epithelial-mesenchymal transition (EMT) to promote the advancement of gastric cancer by activating CDC42 and ITGA5 signaling pathways, with mediation from VAV2." (PMID 37737201, 2023).